ITGA6 (integrin subunit alpha 6)
Diseases named in the same sentence as ITGA6 in open-access papers (continued):
Sharing a sentence is not in itself a finding about the gene and the disease.
breast carcinoma (continued). "For example, CD36 is coexpressed with the stemness markers CD44+/CD133+/ALDH+ in breast cancer, with CD44bright in OSCC, and with CD44+/CD133+/ITGA6+ in GBM." (PMID 36568966, 2022). "Overexpression of ITGA6 and ITGB4 attenuated the ferroptosis induced by erastin, while knockout of ITGA6 and ITGB4 promoted ferroptosis in breast cancer cells." (PMID 34277151, 2021). "HIFs mediate adaptive metabolic responses and mitochondrial ROS production in breast cancer tumour stem cells (BCSCs), enhancing the CSC phenotype via ITGA6 and promoting ALKBH5 expression, which plays a critical role in tumour-initiating breast cancer cells." (PMID 32913192, 2020). "Mammary stem cell markers or combined markers have been certified in different stages of stem cells in breast cancer, including ALDH, CD44, CD24, ITGA6/EpCAM, and PROCR." (PMID 31340763, 2019). "These relationships are particularly relevant to basal-like breast cancers which express higher levels of HIF-dependent target genes and ITGA6 relative to the other common molecular subtypes." (PMID 27001172, 2016). "Our results are particularly relevant to basal-like breast cancers which express higher levels of the HIFα subunits, core HIF-dependent target genes and ITGA6 relative to other molecular subtypes." (PMID 27001172, 2016). "Our data suggest that HIF-dependent regulation of ITGA6 is one mechanism by which sorting for CD49f + cells enhances CSC and metastatic phenotypes in breast cancers." (PMID 27001172, 2016). "ITGA6 is a cell-surface protein which has been shown to identify adult mouse mammary stem cells and a tumorigenic subpopulation in the MCF-7 breast cancer cell line as well as regulating CSCs in glioblastoma." (PMID 22112299, 2011). "Paricalcitol inhibits the expression of ITGA6, ITGB4, and α-SMA in human breast cancer cells." (PMID 40386428, 2025). "It was found in our study that RBM47, PCBP3, FRG1, SRP72 and other RBPs may regulate the AS of ITGA6, ADGRE5, TNC and other genes and affect the EMT process of breast cancer cells." (PMID 38783078, 2024). "RBM47, PCBP3, FRG1, SRP72 and other RBPs might regulate AS of ITGA6, ADGRE5, TNC and other genes and affect the EMT process of breast cancer cells." (PMID 38783078, 2024). "Moreover, TNBCs are also enriched in the expression of transcriptional programs coupled to breast cancer stem cells (e.g., CD44, ITGA6/α6 Integrin, ALDH1A1, and CD133/PROM1) and epithelial–mesenchymal transition (EMT) programs." (PMID 39335212, 2024). "Moreover, individual CSCs in SCC (CD44+CD34+ITGA6+), lung cancer (ASCL1+/CGRP+ neuroendocrine cell) and breast cancer (CD44+CD24-, GSE124887) show concurrent activation of stemness genes, nuclear factors and mitochondrial components." (PMID 37463926, 2023). "Human embryonic stem cells also expressed both spliced isoforms of ITGA6; however, ITGA6-A is required to inhibit the kinase activity of the focal adhesion kinase (FAK) and prevent differentiation, while in breast cancer stem cells, the ITGA6-B isoform is responsible for maintaining the stemness." (PMID 37444576, 2023). "The expression of key markers associated with proliferation (MKI67, PCNA, CCNB1, MYBL2, BUB1, CCND1), apoptosis (BCL2, CASP7, CASP8, CASP9, CASP3, BAX, APAF1), differentiation (CDH1, CD24, EPCAM, ESR1, NGFR, RUNX1), and breast cancer stemness (CD44, ITGA6, DNER, ALDH1A3, ABCG2, PROCR) was assessed." (PMID 35183258, 2022). "Some genes associated with cell adhesion were analyzed from this radiation- and estrogen-induced experimental breast cancer model, including E-cadherin gene CDH1, DSC3, GJA1, the Integrin alpha 6 gene ITGA6, the Integrin beta 6 gene ITGB6, the Keratin genes KRT14, KRT16, KRT17, KRT6B, and LAMB3." (PMID 36293530, 2022).
breast carcinoma (continued). "The high level of CD49f expression in MDA-MB-231 cells is in line with previous observations, where in this and other highly malignant breast cancer cell lines, ITGA6 expression was elevated and mediated radio-resistance via the activation of the PI3K/Akt and MEK/Erk signaling pathways." (PMID 31734558, 2019). "In breast cancer stem cells, ESRP1 is responsible for regulating ITGA6 splicing." (PMID 29401653, 2018). "Here, we showed that compression induces miR-9 downregulation via DNMT3A-dependent promoter methylation, which leads to the upregulation of miR-9 target genes (LAMC2, ITGA6, and EIF4E) thus potentiating signal transduction for VEGFA expression in CAFs and breast cancer cells." (PMID 28252641, 2017). "Thus, our data suggest that HIF-dependent regulation of the ITGA6 gene is one mechanism by which sorting for CD49f + cells enhances CSC and metastatic phenotypes in breast cancers since HIF-1 activity is highest in CD49fHigh cells." (PMID 27001172, 2016). "Notably, CuB inhibited ITGA6 and ITGB4 (integrin α6 & integrin β4), which are overexpressed in breast cancer." (PMID 24729020, 2014). "By establishing the correlation network of differential RBPs and differential AS events, we found that RBM47, PCBP3, FRG1, SRP72, RBMS3 and other RBPs may regulate the AS of ITGA6, ADGRE5, TNC, COL6A3 and other cell adhesion genes, which may affect the EMT process of breast cancer cells." (PMID 38783078, 2024). "In addition, an early phase I clinical study (NCT04289532) employed 99mTc-RWY, a radiotracer for ITGA6-targeting (RWY peptide), to perform single-photon emission computed tomography imaging in breast cancer patients, helping to predict overall survival and prognosis." (PMID 37444576, 2023). "Moreover, a recent study showed that ITGA6 is a hypoxia-inducible factor (HIF)-dependent transcriptional target gene and that ITGA6 expression is an independent prognostic factor in patients with breast cancer." (PMID 28415821, 2017).
bladder cancer (24 papers, 2016 to 2025). "METTL3 can enhance cell adhesion by upregulating ITGA6, which is linked to poor prognosis in bladder cancer." (PMID 36008936, 2022). "A clinical study revealed that in bladder cancer cells, m6A is highly enriched in the ITGA6 transcripts, and increased m6A methylation of the ITGA6 mRNA 3′UTR promotes the translation of ITGA6 mRNA by binding YTHDF1." (PMID 36835655, 2023). "In bladder cancer, after m6A modification of ITGA6, YTHDF1 cooperated with YTHDF3 to promote the translation of ITGA6 and mediated tumor progression." (PMID 36830614, 2023). "It was found that m6A abundantly existed in ITGA6 transcripts, and methyltransferase-like 3 (METTL3) promoted YTHDF1/YTHDF3 binding to the ITGA6 mRNA 3′-UTR, thereby enhancing ITGA6 mRNA translation and changing the adhesion ability of bladder cancer cells." (PMID 36017491, 2022). "Since ITGA6 enhances the growth and metastasis of bladder cancer cells, METTL3 knockout leads to reduced adhesion, proliferation, migration and invasion of bladder cancer cells." (PMID 36008936, 2022). "For example, YTHDF1 promotes the growth and progression of bladder cancer via the ITGA6-METTL3 pathway." (PMID 34026603, 2021). "explored that m6A writer METTL3 and eraser ALKBH5 regulator cell adhesion via embellishing ITGA6 expression in bladder cancer." (PMID 34733275, 2021). "YTHDF3, as one of ‘readers’ of m6A RNA modification, can recognize residues of m6A in ITGA6 and increase ITGA6 expression to promote bladder cancer occurrence." (PMID 33829656, 2021). "Studies also found that YTHDF1/YTHDF3 can preferentially identify the m6A-modified region in the 3 untranslated regions of ITGA6, promoting ITGA6 translation and enhancing the growth and metastasis of bladder cancer cells." (PMID 34604051, 2021). "Additionally, multisite m6A modifications of ITGA6 have been identified to promote bladder cancer (BCa) progression." (PMID 41235257, 2025). "Three other pathways are also associated with METTL3 upregulation in bladder cancer, including the METTL3 -CDCP1 (CUB Domain Containing Protein 1), METTL3-ITGA6(Integrin Subunit Alpha 6), and METTL3/YTHDF2-SETD7/KLF4(SET Domain Containing Lysine Methyltransferase 7/ Kruppel Like Factor 4) m6A axes." (PMID 32765970, 2020). "Therefore, ITGA6 is a crucial target of METTL3 function in bladder cancer." (PMID 32765970, 2020). "In bladder cancer, YTHDF1 promotes bladder cancer growth and progression through the ITGA6-METTL3 pathway." (PMID 36733344, 2023). "The combination of YTHDF1 and YTHDF3 promotes the translation of Integrin subunit alpha 6 (ITGA6) mRNA and the development of bladder cancer." (PMID 33692959, 2021). "In bladder cancer cells, METTL3 and ALKBH5 alter cell adhesion through the m6A methylations of the ITGA6 mRNA 3’UTR20." (PMID 31959747, 2020). "Our analysis revealed that ITGB4/ITGA6 and ITGA5 were significantly downregulated with ISO treatment, suggesting that ISO may suppress cell migration and invasion of bladder cancer cells by decreasing integrin expression and activities." (PMID 38339062, 2024). "Similarly, Jin et al35 found that METTL3 and ALKBH5 regulated the m6A modification of the 3′‐UTR of the oncogene ITGA6 mRNA and that YTHDF1/3 recognized m6A modification to promote ITGA6 translation in bladder cancer." (PMID 32808488, 2020).
colorectal cancer (21 papers, 2015 to 2025). A primary or metastatic malignant neoplasm that affects the colon or rectum. "ITGA6 has also been investigated but it was found that its expression did not influence the association of ITGB4 expression with prognosis in colorectal cancer." (PMID 31877793, 2019). "In the present study, we show for the first time that the proto-oncogene MYC can regulate the promoter activation and splicing of the ITGA6 integrin gene through ESRP2 to favor the production of the pro-proliferative ITGA6A variant in colorectal cancer cells." (PMID 29401653, 2018). "However, the mechanisms that control ITGA6 expression and splicing into the ITGA6A variant over ITGA6B in colorectal cancer cells remain poorly understood." (PMID 29401653, 2018). "Through targeting ITGA6, mesenchymal stem cell-derived exosomal-miR-3940-5p suppresses colorectal cancer cell invasion and EMT." (PMID 37444576, 2023). "Recent study has shown that ITGA6 can be a useful biomarker for early detection of colorectal cancer cells in a noninvasive assay and as a prognostic factor." (PMID 36925653, 2023). "Integrin subunit α 6 (ITGA6), a member of the integrin α chain family of proteins, is an efficient early-detection biomarker and prognostic factor for colorectal cancer patients." (PMID 33682883, 2021). "ITGA6 was notarized to be a target of miR-143-3p, and miR-143-3p degraded the expression of ITGA6 to inhibit colorectal cancer metastases." (PMID 33317527, 2020). "In primary human colorectal cancer cells, the levels of both ITGA6 and β4 integrin subunit (ITGB4) subunits of the α6β4 integrin are increased." (PMID 29401653, 2018). "Pharmacological inhibition of MYC activity with the MYC inhibitor (MYCi) 10058-F4 or knockdown of MYC expression by short hairpin RNA (shRNA) both lead to a decrease in ITGA6 and ITGA6A levels in colorectal cancer cells, while overexpression of MYC enhances ITGA6 promoter activity." (PMID 29401653, 2018). "MiR‐143‐3p targeting integrin α 6 (ITGA6) and with SH3 domain, anchor protein repeat sequence and PH domain 3 (ASAP3), and promote the occurrence and development of colorectal cancer by regulating the expression of both proteins." (PMID 39823268, 2025). "Chromatin immunoprecipitation revealed that the proximal promoter sequences of ITGA6 and ESRP2 were occupied by MYC and actively transcribed in colorectal cancer cells." (PMID 29401653, 2018).
cervical carcinoma (19 papers, 2014 to 2025). A carcinoma arising from either the exocervical squamous epithelium or the endocervical glandular epithelium. "Similarly, knockdown of ITGA6 in SiHa cervical cancer cells also inhibited the efficiency of HPV16 PsV infection (MOI = 1.0)." (PMID 30840887, 2019). "Interestingly, the findings provided by Zhu's study revealed that ITGA6 may be directly targeted by miR-144-3p in cervical cancer and that lncRNA ATB promoted the viability of cell proliferation and invasion through the miR-144/ITGA6 axis." (PMID 34326893, 2021). "ITGA6 (CD49f) might be a possible surface marker of cervical cancer stem cells." (PMID 25362645, 2014). "In cervical cancer, lnc‐ATB promotes proliferation and invasion by regulating the miR‐144/ITGA6 axis." (PMID 33336896, 2021).
prostate carcinoma (19 papers, 2011 to 2024). A carcinoma that arises from epithelial cells of the prostate gland. "The SNP rs12621278 resides near the integrin gene ITGA6 which has been shown to be associated with prostate cancer progression and development." (PMID 31776447, 2020). "In the xenograft human prostate cancer mouse model, treatment with the J8H antibody, which blocks ITGA6 by converting it into ITGA6-p, reduces osteolytic tumor activity and induces a sclerotic reaction in bone lesions." (PMID 37444576, 2023). "ITGA6 is known to be a better marker than CD133 and CD44 in sphere colony-forming cell cultures of prostate cancer cells." (PMID 37444576, 2023). "Our previous studies showed that overexpression of ITGA6/B4 and ITGA3/B1 was involved in cancer cell migration and invasion in HNSCC and prostate cancer." (PMID 28415821, 2017). "Genes involved in steroid synthesis included CYP21A2, HSD17B2, ITGA6, IDI2, MAP2K1, PMVK, TSPO, and may correspond to androgen dependent growth of prostate cancer." (PMID 32226005, 2020). "We focused on Lyn, a member of the Src family, since ITGA6 depletion alters Lyn phosphorylation in acute lymphoblastic leukemia (ALL), increasing sensitivity to chemotherapy and since Lyn could regulate Snail and Slug protein stability in breast and prostate cancer cells." (PMID 38658801, 2024).
lung carcinoma (18 papers, 2007 to 2024). "Nevertheless, a few Sox2 downstream gene targets have been reported in other cancer types, including PROM1 (encoding CD133) in human lung cancer cells and ITGA6 (encoding CD49f) in human mesenchymal stem cells." (PMID 25380620, 2014). "Firstly, the precise targeting and regulation of molecules such as SMAD3 and ITGA6 in patients with lung cancer remains relatively challenging given the current technological level." (PMID 38493128, 2024). "Early studies have reported that ITGA6 is involved in the occurrence and development of lung cancer." (PMID 32489333, 2020). "Specifically, knocking ITGA6 down in lung cancer cells decreases their invasiveness." (PMID 39329988, 2024). "We created a score combining the expression of CDKN1A, ITGA6, and SNAI1, which was an independent prognostic biomarker for lung cancer patients." (PMID 31506430, 2019). "Based on the results of their analysis, the authors recommend ITGB4 rather than ITGA6 as an adverse prognostic biomarker for lung cancer." (PMID 39329988, 2024). "CD49f, (integrin subunit alpha 6, ITGA6), is also identified to be a CSC surface marker, and found to correlate with tumor spheres formation capacity and in vivo self-renewal ability in lung cancer." (PMID 33588867, 2021). "Furthermore, EMP1, expression of which was higher in the glucose-cultured ITGA6 positive cells, is a biomarker of resistance to another TKI, gefitinib, in lung cancer." (PMID 29796188, 2018).
glioblastoma (17 papers, 2013 to 2025). The most malignant astrocytic tumor (WHO grade IV). "Its mapping of co‐expression combinatorics and its finding of a CD44+/CD133+/ITGA6+/CD36+ molecule signature on gliomaspheres is a relevant step towards a more complete understanding of stemness‐associated molecules in glioblastoma." (PMID 30467961, 2019). "At the molecular level, various cancer-related pathways (such as FAK, ERK/MAPK, Src, AKT, and Ras) are activated due to elevated levels of ITGA6, thereby promoting the stemness of glioblastoma." (PMID 39239559, 2024). "Data also suggest that ITGA6 inhibition counters radiotherapy resistance in mesenchymal glioblastoma stem-like cells." (PMID 38493128, 2024). "ITGA6 can regulate the expression of FGFR1 in glioblastoma stem cells through the ZEB1/YAP1 transcription complex and upregulate the proliferation and stemness of GBMSCs by synergistically interacting with FGFR1." (PMID 39239559, 2024). "Potential clinical significance of our findings is due to the ability to target ITGA6 in glioblastoma cells via newly identified action of sGCβ1." (PMID 36900358, 2023). "Clinical relevance of ITGA6 was demonstrated using an in silico glioblastoma patient database to demonstrate that ITGA6 expression inversely correlates with survival (p = 0.0129)." (PMID 36900358, 2023). "In glioblastoma stem cells, ITGA6 and fibroblast growth factor receptor 1 (FGFR1) have a synergistic effect in their development and tumor spheroid growth." (PMID 37444576, 2023). "Integrin alpha 6 (ITGA6) has received considerable attention due to its role in the regulation of glioblastoma stem-like cells." (PMID 36900358, 2023). "Examination of ITGA6 expression in biopsy samples from glioblastoma patients indicated that ITGA6 is coexpressed with conventional glioblastoma stem-like cell markers and that ITGA6 is enriched in the perivascular niche." (PMID 36900358, 2023). "ITGA6 has been identified as a glioblastoma stem-like cell marker." (PMID 37444576, 2023). "The data of the present study showed a marked expression of ITGA6 in U87 glioblastoma cells." (PMID 36900358, 2023). "ITGA6 is commonly used as a glioblastoma stem-like cell (GSC) marker." (PMID 36835655, 2023). "Finally, we investigated the relation of the identified CD44+/CD133+/ITGA6+/CD36+ signature to the four glioblastoma molecular subtypes (mesenchymal, neural, proneural, and classical) as well as the isocitrate dehydrogenase 1 (IDH1) status." (PMID 30467961, 2019). "Theoretically, it might be that after all these experiments, cells with the CD44+/CD133+/ITGA6+/CD36+ signature can indeed be described as a phenotype especially characteristic of stem‐like glioblastoma cells." (PMID 30467961, 2019). "Additionally, studies suggest that the regulatory role of ITGA6 on glioblastoma stemness may be controlled by Kruppel-like factor-9 (KLF9)." (PMID 39239559, 2024). "Thus, ITGA6 expression is elevated in glioblastoma stem-like cells, and this protein may be a target for therapeutic development." (PMID 36900358, 2023). "Researchers have identified three subgroups of stem cells in glioblastoma stem cells: mesenchymal (MES), proneural (PN), and classical (CL), with ITGA6 maintaining the stemness of PN-GSCs but enhancing the radiotherapy resistance of MES-GSCs." (PMID 39239559, 2024). "ITGA6 expression strongly decreased upon differentiation stimuli together with NES expression and was totally undetectable in differentiated glioblastoma cells (DGCs) derived from the same post-surgical specimen." (PMID 34205341, 2021). "Next, to assess the potential clinical importance of the core 4‐marker signature identified (CD44, CD133, ITGA6 and CD36), we analysed publicly available glioblastoma gene expression and survival datasets from the TCGA." (PMID 30467961, 2019).